CCL2 (C-C motif chemokine ligand 2)
Diseases named in the same sentence as CCL2 in open-access papers (continued):
Sharing a sentence is not in itself a finding about the gene and the disease.
breast cancer (continued). "In breast cancer models, overexpression of CCRL2 has been shown to inhibit CCL2-induced p38 MAPK phosphorylation, resulting in restored E-cadherin expression and reduced cellular invasiveness." (PMID 40867595, 2025). "Overall, these data indicate that CCR2 overexpression increases responsiveness to CCL2 and HGF in SUM225 breast cancer cells." (PMID 40736024, 2025). "In breast cancer, estrogen enhances Twist expression by activating ERα and PI3K/AKT/NF-κB signaling, which in turn induces CCL2 autocrine." (PMID 41341593, 2025). "CCL2 and CCL5 are among the most extensively studied chemokines in the breast cancer microenvironment." (PMID 40909271, 2025). "Overall, these data indicated that CCL2, HGF and CCL2/HGF co-treatment led to changes in overlapping and unique metabolic pathways in breast cancer cells." (PMID 40736024, 2025). "Mechanistically, M2 enhances tumor survival via pathways like CCL2/PI3K/Akt/mTOR in breast cancer, IL-6/STAT3 in colon and pancreatic cancers, and CHI3L1 in gastric/breast cancers." (PMID 40940877, 2025). "In summary, CCL2 and HGF co-treatment enhanced proliferation, survival, and invasion in DCIS.com and HCC1937 breast cancer cells over CCL2 or HGF alone, with some differences in responsiveness to CCL2 and HGF between the cell lines." (PMID 40736024, 2025). "Given the associations between CCL2 and HGF expression in breast tissues, we compared the effects of CCL2 and HGF co-treatment with a single treatment on breast cancer cell lines." (PMID 40736024, 2025). "In human breast cancer, CAFs recruited monocytes via MCP1, CXCL12, CCL2, and CCL16, leading to their differentiation into M2-like macrophages that exert immunosuppressive effects through the PD-1 axis." (PMID 40230452, 2025). "CCL2/HGF-mediated cellular phenotypes were associated with increased AMPK, p42/44MAPK, AKT and PKC signaling, indicating cooperative roles for CCL2 and HGF signaling in breast cancer for both cell lines." (PMID 40736024, 2025). "Specifically, CCL2 triggers phosphorylation of MET receptor tyrosine kinases, inducing proliferation, migration, and glycolysis in breast cancer cells." (PMID 39749673, 2025). "Although anti-CCL2 mAb significantly reduced TAMs in the TME during treatment, withdrawal of the antibody leads to accelerated metastasis of breast cancer cells due to the rapid rebound of monocyte recruitment." (PMID 39003350, 2024). "Estradiol was reported to enhance macrophage influx and angiogenesis by increasing the release of CCL2, CCL5, and EGF in estrogen-positive breast cancers." (PMID 39003350, 2024). "Reduced interaction between CCL2 and CCR2 on breast cancer cells can hinder their migration and survival, possibly through diminished activation of Smad3 or MAPK signaling." (PMID 38360633, 2024). "In models of breast cancer lung metastasis, the activation of macrophages expressing CCR2 by CCL2 leads to the production of CCL3, which in turn mediates TAM retention via CCR1 signaling." (PMID 39201480, 2024). "While chronic hypoxia downregulates the CCL2 expression in ovarian cancer, and HUVEC, the CCL2 upregulation was evident in gastric cancer, breast cancer cells, dermal fibroblasts, and primary mouse astrocytes." (PMID 35658112, 2024). "So, we conclude that CAV1 in BC-derived sEVs promote neutrophil recruitment through the TLR4-NF-κB-IL-6/CCL2 axis and neutrophil N2-type polarization through the TLR4/NF-κB/NLRP3 pathway, thus promoting the lung metastasis of breast cancer." (PMID 39494337, 2024). "TNF-α stimulates the stromal cells and releases elevated levels of CCL2, CXCL8, and CCL5, which have tumor-promoting solid activities in general and breast cancer, mainly when derived from stroma cells." (PMID 38541912, 2024). "This concordance suggests a somewhat coordinated coexpression of the chemokines CCL2 and CCL5 in MIBC, as has been reported in breast cancer." (PMID 38928033, 2024).
breast cancer (continued). "Conversely, stimulated NK cells can produce T-cell-recruiting chemokines, including CCL2 and CCL5, in breast cancer patients." (PMID 38928033, 2024). "This case-control study emphasized the importance of having sufficient sample sizes to achieve a thorough assessment of the relationship between the CCL2, and CXCL12 SNPs and breast cancer." (PMID 39703847, 2024). "In lung and breast cancer cells, 6‐shogaol inhibits the phosphorylation of STAT3 and decreases the CCL2 expression, preventing the effects of TADCs on tumorigenesis and metastasis in vivo and in vitro." (PMID 39055196, 2024). "For instance, CCL2 has been reported to promote proliferation and cell cycle progression by activating SRC and PKC in basal-like breast cancer cell lines." (PMID 38167009, 2024). "The CCL2/CCR2 axis is involved in inflammatory responses and the growth and metastasis of many tumors, including breast carcinoma and pancreatic ductal adenocarcinoma." (PMID 39376728, 2024). "The CAAs modulate, for instance, the behavior of breast cancer cells via the release of pro-inflammatory mediators such as IL-6, TNF-α, CCL2, or CCL5, promoting angiogenesis, proliferation, and metastasis." (PMID 37686315, 2023). "Thus, CCL2 may be a potential prognostic marker for lung metastasis in breast cancer patients." (PMID 37563136, 2023). "In turn, breast cancer cells release TNF-α, activate mTORC1/FOXK1 in TAMs and stimulate M2 polarization with elevated release of CCL2, thereby forming a positive feedback mechanism and offering therapeutic resistance." (PMID 37900137, 2023). "Together, these data reveal a positive correlation between the expression of TNC and CCL2 in HER2+ breast cancer and show that TNC is required to maintain high levels of CCL2 expression in tumor cells." (PMID 37176074, 2023). "The RNA binding protein EIF4A3 is considered as an important regulator of post-transcriptional regulatory processes, and CCL2, as a powerful macrophage chemokine, was reported to be a target of STAT3 in breast cancer." (PMID 36797769, 2023). "More interestingly, aerobic exercise plays a protective role in primary cancer development and progression by regulating the levels of chemokines CCL2, CCL5, and their related receptors CCR2, and CCR5 in breast cancer." (PMID 36976529, 2023). "uncovered that in breast cancer, FBXW7 deletion activates CCL2 promoter by reducing NOTCH turnover, which recruits monocytic myeloid-derived suppressor cells (Mo-MDSCs) and TAMs to the premetastatic niche and accelerates tumor metastasis and immunosuppression." (PMID 37658431, 2023). "Another study showed that cytotoxic chemotherapy induced cellular senescence in hematopoietic tissues of breast cancer patients and prolonged the increase in SASP factors VEGFA and CCL2 levels." (PMID 37251343, 2023). "The pro-inflammatory stimulation from TNFα promotes MCP1/CCL2 signaling, which is a mediator of metabolic adaptations in cells and induces increased glycolysis in breast cancer cells." (PMID 37107188, 2023). "In another study, TAMs increased CCL2 secretion through M2 polarization and activated the PI3K/Akt/mTOR signaling pathway in breast cancer cells, promoting endocrine resistance." (PMID 37889551, 2023). "In breast cancer, TAM-secreted CCL2 promotes an endocrine resistance by activating the PI3K/AKT/mTOR signaling pathway." (PMID 37272931, 2023). "An elevated expression linked to enhanced tumor growth is recapitulated in experimental models of breast cancer, including orthotopic syngeneic grafting models, where TNC or CCL2 expression contributes to disease progression." (PMID 37176074, 2023). "Cochrane’s Q test did not provide evidence of heterogeneity between CCL1 (p = 0.227), CCL2 (p = 0.982), CCL18 (p = 0.221), CXCL5 (p = 0.533), CXCL12 (p = 0.977), and CXCL13 (p = 0.520) and breast cancer." (PMID 38075694, 2023).
breast cancer (continued). "In lung fibroblasts, CXCL1, as well as other CXCR2 ligands, increases the expression of CCL2/MCP-1 and CCL7/MCP-3, both of which increase cholesterol synthesis in breast cancer cells in the lung." (PMID 37108425, 2023). "For instance, CXCL12, CCL2, CCL5, and CXCL1 have been shown to regulate growth and stimulate the proliferation of melanoma, glioma, prostate cancer cells, and breast cancer cells." (PMID 37762405, 2023). "In summary, MET receptor activity is an important mechanism for CCL2/CCR2-mediated progression and metabolism of early-stage breast cancer, with important clinical implications." (PMID 35405500, 2022). "This study described a robust positive correlation between miR-375 and CCL2 levels and miR-375 and TAM infiltration in invasive human breast cancer biopsies." (PMID 36248881, 2022). "Another report describes a similar mechanism whereby M2-polarized TAMs secrete CC chemokine ligand 2 [CCL2 also known as MCP-1)], which activates the PI3K/Akt/mTOR signaling pathway and promotes tamoxifen resistance in endocrine‐resistant breast cancer cells." (PMID 35646668, 2022). "As a result, CCL2 and CCL2/CCR2 as therapeutic targets for breast cancer remain to be further investigated." (PMID 36403055, 2022). "The detection of plasma CCL2 and CCR2 combined with CA 15-1 can be used as a biomarker for breast cancer diagnosis." (PMID 36403055, 2022). "In recent studies, MIND injection of transformed and patient derived breast cancer cells resulted in DCIS, which became invasive with CCL2 treatment." (PMID 35405500, 2022). "Overall, these data indicate that: CCL2 triggers interactions among CCR2, MET and SRC in breast cancer cells, and CCL2 regulates MET phosphorylation through CCR2- and SRC-dependent mechanisms." (PMID 35405500, 2022). "The C-C Ligand 2 (CCL2) and its primary receptor CCR2 are key regulators of macrophage recruitment, and their expression are upregulated in prostate, glioma and breast cancers." (PMID 35405500, 2022). "In breast cancer, with CCR2 (the chemokine receptor for CCL2) expressed, inflammatory monocytes are more promising to accumulate in the pulmonary metastases than in primary tumors." (PMID 35911705, 2022). "It has been observed that in the mouse 4T1.2 mammary cancer model, pro-inflammatory monocytes with MDSCs features (IL4R, CD49b, CD62L, CD11b) can be recruited by the chemokine CCL2 in the pre-metastatic lungs where they foster metastasis." (PMID 35309358, 2022). "Chemokine (C-C motif) ligand 2 (CCL2; MCP-1) secreted by CAF can induce blood monocyte recruitment and differentiate into TAMs in breast cancer." (PMID 35464435, 2022). "The present research has confirmed that blocking the CCL2/CCR2 axis can prevent the growth of prostate and breast cancer cells." (PMID 36403055, 2022). "Here, we sought to understand the molecular mechanisms through which CCL2/CCR2 signaling regulated DCIS progression using in vitro and in vivo breast cancer models." (PMID 35405500, 2022). "Furthermore, studies have shown that CCL2 is highly expressed in tumor epithelial cells, and many CD14-positive cells are infiltrated in primary tumors, implying that high levels of CCL2 and CD14-positive cells can serve as diagnostic markers for early recurrence of breast cancer." (PMID 36403055, 2022). "CAFs have been reported to facilitate the maintenance of breast cancer cell stemness via the CCL2/NOTCH1 pathway, and perostin, which is an important component of the ECM derived from fibroblasts, is essential for sustaining breast cancer stemness." (PMID 36244987, 2022). "The second important chemoattractant is CCL2, which was secreted by mammary tumors and which recruited CCR2-expressing inflammatory monocytes to pulmonary metastatic sites of breast cancer." (PMID 35267547, 2022).
breast cancer (continued). "Inhibition of CCL2 could break this loop and reverse the enhanced BC cell tumor proliferation and migration caused by EZH2 inhibitors, which suggested that combinational inhibition of CCL2 with EZH2 inhibitors may be beneficial to the treatment of breast cancer." (PMID 36038549, 2022). "Previous studies have reported that overexpression of CCL2 and its receptors, CCR2, and CCR4, in human cancers, promote lung cancer, breast cancer, and HNSCC development via regulation of angiogenesis, cell proliferation, and migration." (PMID 35177591, 2022). "Our previous work with breast cancer patients demonstrated that high levels of TGF-β, TNF-α, VEGF, IL-6, IL-8, and IL-10 correlated with poor prognosis, while IL-21 and CCL-2 are related to a better outcome." (PMID 36428939, 2022). "Though CCL2/CCR2 signaling is known to promote late-stage tumor growth and metastasis by enhancing macrophage recruitment to the primary tumor, CCL2 increases tumor cell growth, survival and migration by signaling to CCR2 overexpressing breast carcinoma cells." (PMID 35405500, 2022). "In breast cancer cells, Lnc-BM increased the STAT3-dependent expression of ICAM1 and CCL2, which regulated vascular co-option and recruitment of macrophages in the brain, respectively." (PMID 34123857, 2021). "In vitro studies have shown that CCL2 can increase MMP-9 expression in human chondrosarcoma cells, in NSCL A549 cell migration and in human breast cancer MCF-7 cells." (PMID 34804061, 2021). "Another research group reported that circulating exosomes secreted by breast cancer cells increased macrophage NF-κB activation and induced proinflammatory activity by upregulation of inflammatory cytokines IL-6, TNFα, GCSF, and CCL2." (PMID 34207035, 2021). "Further analysis revealed that CCL2 secreted by TAMs activated the PI3K/AKT/mTOR pathway in tumor cells, thus inducing resistance to tamoxifen treatment in breast cancer cells." (PMID 34178692, 2021). "In breast cancer, lnc-BM increased JAK2 kinase activity to mediate oncostatin M- and IL-6-triggered STAT3 phosphorylation, promote ICAM1 and CCL2 expression, and mediate macrophage recruitment to the brain and consequently metastasis." (PMID 34123857, 2021). "Prolonged blood circulation, high tumoritropic accumulation, proactive recruitment capacity from CCL2/CCR2, and α4/VCAM‐1 active targeting property were achieved by QE‐loaded BS‐NPs@MφCM NPs, resulting in the inhibition of lung metastasis of breast cancer." (PMID 33898169, 2021). "Elevated CCL5 (RANTES), CCL2 (MCP-1), and CXCL8 (IL-8) in TNFα/IL-1β primed triple-negative subtype of breast cancer cells (TNBCs): hBMMSCs co-cultures increase BCC lung metastases." (PMID 33849537, 2021). "Overall, these studies demonstrate that CCR2 antagonists impair CCL2/CCR2 mediated growth and signaling of breast cancer cells in vitro." (PMID 33888841, 2021). "In a mouse model of breast cancer, doxorubicin treatment led to recruitment of CCR2-expressing monocytic cells by stroma-derived CCL2, dampens treatment response and promotes tumor re-emergence." (PMID 34439387, 2021). "Here, we studied the behavior of the CCL2 gene in MDA-MB-231 and HCC1937 breast cancer cells representing mesenchymal-like phenotype activated by TGF-β." (PMID 34239022, 2021). "In a model of lung metastasis of breast cancer, CCR2+ MØs upon activation by CCL2 produce CCL3 to induce CCR1-mediated TAM retention in the lung, supporting involvement of multiple chemokines and receptors in tumor metastasis." (PMID 34804061, 2021). "For example, the binding of CCL2 and CCR4 is involved in mammary gland development and promotes breast cancer progression." (PMID 34464477, 2021). "A direct correlation between the CCL2 and TGF-β levels is typical for progressive stages of breast cancer as was recently shown using both clinical samples and in vitro studies." (PMID 34239022, 2021).
breast cancer (continued). "In a model of breast cancer, the secretion of IL-1β and TNF-α by transformed cells and immune cells, activates in bone marrow MSCs NF-κB pathway and chemokine secretion like CCL2 and CXCL8/IL-8 that favor an inflammatory TME promoting monocyte migration." (PMID 34680425, 2021). "Our findings illustrated that Notch3-regulating CCL2/CCR4 axis should be an important signaling pathway for mammary gland development and should be a candidate target for breast cancer therapy." (PMID 33244467, 2020). "In the TCGA breast cancer data, (U.C. Santa Cruz, xenabrowser.net, Nature 2012), two of the factors in this study (PARP1 and CCL2) showed significant overexpression in the Basal type of tumors concerning the Luminal-A or B subtype." (PMID 32455851, 2020). "Collectively, we identify S100A14 as an upstream regulator of CCL2/CXCL5 signaling and a metastatic driver of breast cancer." (PMID 32483412, 2020). "CCL2-mediated TAM recruitment is critical for the progression and malignant conversion of mammary tumors in the PyMT model." (PMID 32300202, 2020). "For example, CCL2, CCL5, CXCL8, and CXCL12 can promote breast cancer, while CXCL9, CXCL10, and CCL16 can inhibit breast cancer." (PMID 32253815, 2020). "Consistent with previous results, CDDO-Me treatment inhibits TAM infiltration to mammary tumors, and decreases TAM expression of the macrophage chemo-attractant CCL2." (PMID 32300202, 2020). "Since CCL2 mediated cell signaling pathway activation and PARP1 inhibition are negatively correlated in breast cancer cells, we compared whole transcriptome profiles of MB-231 with rhCCL2 or PJ34 treatment." (PMID 32455851, 2020). "The chemokine CCL2 mediates the prometastatic effects of dysadherin in cancer cells, notably in ER-negative MDA-MB-231 breast cancer cells." (PMID 32085612, 2020). "Aggressive types of breast cancer, like TNBCs, have been shown to have “secretome” comprised of higher concentrations of chemokines such as CXCL1 and CCL2." (PMID 32455851, 2020). "Adipocytokines such as TNF-α, IL-1β, FGF-2, and CCL2, have been found to increase LOX expression in breast cancer." (PMID 33123472, 2020). "Therefore, the obtained findings indicate that butein might be a potential candidate for breast cancer therapy targeting CCL2 in Caucasians and may also provide an explanation regarding the poor response to therapy in African American patients with advance TNBC." (PMID 31665136, 2019). "The mRNA and protein expression of both CCL2 and CCL5 by IFN-γ activated breast cancer cells were significantly reduced in a dose-dependent manner by ZA treatment." (PMID 30808421, 2019). "Increased angiogenesis is seen in susceptible mammary tissue in mouse models that overexpress Cox2 or Ccl2, and reduction of angiogenesis by genetic ablation of Cox2 significantly reduces MMTV-Erbb2/Neu-induced mammary tumor incidence." (PMID 30651598, 2019). "Several investigations also emphasized IL6, IL8, CCL2, and CCL5 as stimulators of the survival, proliferation, and invasion of breast cancer cells." (PMID 31398937, 2019). "In summary, CCL2 has the potential to drive via IL-1β the γδ T cell/IL17/neutrophil axis, which promotes breast cancer metastasis." (PMID 31921102, 2019). "ER- breast cancer has been correlated with increased NF-κB activity and increased expression of certain cytokines (IL-6, IL-8) and chemokines (CCL5, MCP-1 [CCL2])." (PMID 30736340, 2019). "The chemokine monocyte chemoattractant protein-1 (MCP-1)/CCL2 is a chemoattractant that plays an important role in the recruitment of blood monocytes into tumors and known to promote lung metastasis of breast cancer cells." (PMID 31888216, 2019). "Chemokines such as CCL2, CCL5, CCL4, and CXCL8 are also involved in the incidence and development of breast cancer." (PMID 31398937, 2019).